CASR (calcium sensing receptor)
Diseases named in the same sentence as CASR in open-access papers (continued):
Sharing a sentence is not in itself a finding about the gene and the disease.
ovarian carcinoma (5 papers, 2016 to 2024). A malignant neoplasm originating from the surface ovarian epithelium. "More evidence for a link between CaSR and ovarian cancer is given by the observation that the G allele of the CaSR rs17251221 polymorphism seems to protect against ovarian cancer." (PMID 27625611, 2016). "The exact role of CaSR the development of ovarian cancer remains to be determined." (PMID 27625611, 2016). "In addition, exosomal miR-429 was demonstrated to enhance the proliferation and drug resistance of ovarian cancer cells by targeting the calcium-sensing receptor (CASR)/STAT3 pathway, which indicates that miR-429 may act as a primary regulator of chemoresistance." (PMID 38002073, 2023).
pancreatic cancer (5 papers, 2013 to 2025). "Single nucleotide polymorphism (SNP) in vitamin-D-related genes is associated with CaSR, a pancreatic cancer-risk gene, suggesting a strong correlation between vitamin D and pancreatic cancer." (PMID 39781525, 2025). "When analyzed by genotype, a few SNPs in CASR and RXRA were associated with pancreas cancer risk; however, only one was significant in the log-additive models." (PMID 23826131, 2013). "SNPs in the CYP24A1, CYP2R1, calcium sensing receptor (CASR), vitamin D binding protein (GC), retinoid X receptor-alpha (RXRA) and megalin (LRP2) genes were significantly associated with pancreas cancer risk." (PMID 23826131, 2013). "A study also revealed that CaSR expression was decreased in the case of pancreatic cancer." (PMID 36275616, 2022). "CaSR activation markedly suppresses pancreatic tumourigenesis, possibly through sodium-calcium exchanger 1-mediated Ca2+ influx; this leads to the inhibition of Wnt/β-catenin signalling in pancreatic cancer cells." (PMID 29348629, 2018).
urolithiasis (5 papers, 2015 to 2025). Stone(s) within the urinary tract. "Crude odds ratios (ORs) with 95% confidence intervals (CIs) were calculated to estimate the strength of associations between CaSR polymorphisms and the risk of urolithiasis." (PMID 25705702, 2015). "Several investigators tried to examine associations between CaSR polymorphisms and urolithiasis risk, but the conclusions were conflicting." (PMID 25705702, 2015). "At present, several studies have attempted to investigate associations between CaSR gene variants with urolithiasis and urinary calcium concentration." (PMID 25705702, 2015). "Secondly, more case-control studies or updated meta-analyses should be conducted to clarify the possible roles of CaSR polymorphisms in the etiology of urolithiasis." (PMID 25705702, 2015). "Last but not least, this is the first meta-analysis regarding the comprehensive assessment of the relationship between CaSR polymorphisms with urolithiasis risk and urine calcium concentration." (PMID 25705702, 2015). "To fill this gap, we performed a meta-analysis of all eligible studies to derive more reliable estimation of associations between calcium-sensing receptor gene polymorphisms with urolithiasis and urinary calcium concentration." (PMID 25705702, 2015). "For the associations between CaSR polymorphisms and urolithiasis, a total of seven papers which included 10 case-control studies for the A986S polymorphism, 9 case-control studies for the R990G polymorphism, and 4 case-control studies for the Q1011E polymorphism were involved in this meta-analysis." (PMID 25705702, 2015). "As a consequence, the CaSR gene is a candidate to explain the susceptibility to urolithiasis." (PMID 25705702, 2015). "Hence, CaSR plays an important role in urolithiasis and it is rational to hypothesize that its gene polymorphisms may be related to urolithiasis risk." (PMID 25705702, 2015). "Thus, we thought that CaSR polymorphisms might be involved in urolithiasis via influencing activities of CaSR gene and H-pump." (PMID 25705702, 2015). "Although no specific gene has been declared to be the underlying cause of urolithiasis, many functional genes such as urokinase, vitamin D receptor gene (VDR), and calcium-sensing receptor gene (CaSR) have been verified to be related to urolithiasis." (PMID 25705702, 2015). "For instance, enzymes involved in oxalate production, such as glycolate oxidase (GO) and phosphoethanolamine cytidylyltransferase (PEC), as well as receptors involved in calcium homeostasis like the calcium-sensing receptor (CaSR), play critical roles in urolithiasis." (PMID 40364353, 2025). "A growing body of evidence shows that the CaSR might play a crucial role in the pathogenesis of urolithiasis." (PMID 25705702, 2015). "It is widely accepted that CaSR may be connected with urolithiasis, since it decreases calcium reabsorption in thick ascending limbs and distal convoluted tubules, increases phosphate reabsorption in proximal tubules, and decreases water and proton reabsorption in collecting ducts." (PMID 25705702, 2015). "A number of genetic markers in different urolithiasis genes including SPP1, VDR, CaSR, urokinase, prothrombin, interleukins and others have been investigated in this regard." (PMID 32842990, 2020).
breast tumors (4 papers, 2016 to 2024). "Altered signaling through the CaSR has been linked to the development of various tumors, such as colorectal and breast tumors." (PMID 37511437, 2023). "An alteration in the signaling pathway of the CaSR has been associated with the development of a variety of tumors including colorectal and breast tumors, where the role of the CaSR has been described as that of a tumor suppressor in the former and that of an oncogene in the latter." (PMID 37511437, 2023). "Overall, this retrospective case-control study reveals that decreased sensitivity of the CaSR to calcium due to inactivating polymorphisms at rs1801725 may predispose BC patients to high circulating calcium-driven larger or aggressive breast tumors." (PMID 28764683, 2017). "Although the CaSR is pivotal in calcium homeostasis, its contribution in the previously reported association of high calcium with larger or more aggressive breast tumors remain unclear." (PMID 28764683, 2017). "A different study in 3663 cases and 4687 controls of women of African American descent did not replicate these associations but did find that another CaSR SNP (rs112594756) was associated with estrogen receptor status in breast tumors." (PMID 27746743, 2016). "Finally, we examined CaSR protein expression using the semi-automated immunofluorescence AQUA platform in a tissue microarray consisting of 652 breast tumors with a median clinical follow up of 8.9 years (YTMA49)." (PMID 27746743, 2016). "One study showed that BRCA1 regulates the expression of CaSR in MCF-7 and MDA-MB-231 cells but it is not known whether breast tumors in patients with BRCA1 mutations have different levels of CaSR expression than non-BRCA1-associated tumors." (PMID 27746743, 2016).
chronic pancreatitis (4 papers, 2014 to 2024). A chronic inflammatory process causing damage and fibrosis of the pancreatic parenchyma. "The CASR R990G variant has been reported to be significantly associated with chronic pancreatitis and in subjects who reported moderate alcohol consumption." (PMID 36699452, 2022). "A population-based genetic study indicated that calcium sensing receptor polymorphisms showed relation to risk of chronic pancreatitis among the general population and individual with moderate to heavy alcohol consumption." (PMID 33782414, 2021).
heart failure (4 papers, 2018 to 2024). Inability of the heart to pump blood at an adequate rate to meet tissue metabolic requirements. "The CaSR induces Ca2+ release from the ER and its transfer into the mitochondria, leading to mitochondrial depolarization, which is mediated by the mitochondria-associated ER membranes (MAMs), and it is a potential treatment target in cardiac ischemia–reperfusion injury and heart failure." (PMID 36231037, 2022).
injury (4 papers, 2013 to 2023). Damage inflicted on the body as the direct or indirect result of an external force, with or without disruption of structural continuity. "The identification of the activation of CaSR-mediated protective pathway in mRTEC cells sheds light on a possible cellular protective mechanism against Cd-induced kidney injury." (PMID 29348484, 2018).
Insulin resistance (4 papers, 2015 to 2024). Increased resistance towards insulin, that is, diminished effectiveness of insulin in reducing blood glucose levels. "In conclusion, we suggest that decreased Ca2+ levels and increased CaSR expression might be involved in increased insulin secretion to compensate for insulin resistance in aged mice." (PMID 27441644, 2016). "In addition, the CaSR is expressed and functionally active in adipocytes, and may potentially regulate the peripheral actions of insulin, as highlighted by the finding of an association with the A986S CASR polymorphism and insulin resistance in patients with the polycystic ovarian syndrome." (PMID 25786244, 2015). "Previous studies have suggested that the pathological mechanism of insulin resistance in PCOS is related to calcium homeostasis, and CASR as an important calcium regulator may play an important role in PCOS pathogenesis." (PMID 38347589, 2024).
insulinoma (4 papers, 2017 to 2025). "If the CaSR was essential in insulin secretion it would be expected that its expression would be maintained in insulinomas." (PMID 39579056, 2025). "Our study reveals that CaSR expression is significantly reduced in gastrinomas, insulinomas, and NF‐PNETs and that the CASR locus is highly methylated with closed chromatin formation in the NET cell line QGP‐1." (PMID 39579056, 2025). "Our finding that the CaSR is down‐regulated in gastrinomas, insulinomas, and NF‐PNETs suggests that common pathways are dysregulated in these tumours." (PMID 39579056, 2025). "Normal islets adjacent to the NETs could be identified in eight patients (four insulinomas and four NF‐PNETs), and as with the non‐adjacent normal islets highly expressed CaSR." (PMID 39579056, 2025). "Quantification demonstrated that CASR mRNA expression was significantly higher in normal islets (mean relative expression = 1, range = 0.46–1.30) when compared to gastrinomas, insulinomas, and NF‐PNETs (mean relative expression = 0 and p < .0001 for all tumour subtypes)." (PMID 39579056, 2025). "Previous studies have found that Ca levels in the circulation were elevated in patients with insulinoma following a selective arterial calcium injection test and may stimulate insulinoma secretion and its mechanism may be related to the calcium-sensing receptor (CaSR) gene." (PMID 35698198, 2022). "Using RNA‐Scope and quantitative PCR analyses in two independent tumour cohorts from Europe (n = 18 patients) and the USA (n = 46 patients) we showed that CASR mRNA is almost completely absent in gastrinomas, insulinomas and non‐functioning pancreatic NETs." (PMID 39579056, 2025). "Differential expression of UCH-L1, MAP1B, MAP2, VCAN, CDK4 and PDX-1 was verified in more than 40 PNETs, including insulinomas and non-insulinomas by IHC but the expression of CaSR was only validated in 29 insulinomas." (PMID 28526880, 2017). "The non-response of the insulinoma to SACST in this case may be attributed to its unique vascular supply due to its protruding location or an incidental low expression of calcium sensing receptor." (PMID 40405975, 2025). "Our data showing reduced CaSR expression in insulinomas would suggest that insulin secretion is not dependent on CaSR signalling, and therefore, the CaSR may be playing additional roles in these tumours." (PMID 39579056, 2025). "To determine whether CaSR expression is altered in GEP‐NETs, we examined RNA and protein levels in a cohort of FFPE tissues from the Medical University of Vienna, consisting of six normal pancreatic tissue samples, six gastrinomas, six insulinomas, and six NF‐PNETs." (PMID 39579056, 2025).
medullary thyroid carcinoma (4 papers, 2014 to 2022). "Additionally, we show that in human medullary thyroid carcinoma cells (TT), a significant reduction in the signalling of the CaSR when RAMP1 is knocked down or blocked with a RAMP1 antibody." (PMID 24454825, 2014).
melanoma (4 papers, 2020 to 2025). A malignant, usually aggressive tumor composed of atypical, neoplastic melanocytes. "We also identified mutations in three genes (SLC9A2, CASR, SLC8A3) never reported in melanoma, which might deserve further investigations." (PMID 32241263, 2020).
multiple endocrine neoplasia type 1 (4 papers, 2020 to 2023). An autosomal dominant tumor predisposition syndrome caused by pathogenic variants in the MEN1 gene, characterized by an increased risk of tumors of the parathyroid glands, pituitary gland, and foregut neuroendocrine tumors (most commonly pancreatic islet cells). "At a median age of 10.8 (2.0–14.4) years, 18 patients received cinacalcet for primary HPT (N = 13 inactive CASR mutation, N = 1 CDC73 mutation, N = 1 multiple endocrine neoplasia type 1, N=3 unknown etiology)." (PMID 36090548, 2022).
myocardial ischemia (4 papers, 2016 to 2023). A disorder of cardiac function caused by insufficient blood flow to the muscle tissue of the heart. "The expression of CaSR influences autophagy and angiogenesis to defer the cell migration and apoptosis, and can thereby play an important role in myocardial ischemia." (PMID 33804544, 2021). "The involvement of CaSR in myocardial ischemia is a debatable topic as it promotes ischemia and protects the myocardium against it." (PMID 33804544, 2021). "Next, we intend to co-culture CaSR-transfected lymphocytes with rat cardiomyocytes under hypoxic conditions imitating myocardial ischemia to further observe the role of CaSR in T lymphocytes on cardiomyocytes." (PMID 27563892, 2016).
prostate tumors (4 papers, 2016 to 2024). "A recent study showed that high calcium-sensing receptor (CaSR) expression in primary prostate tumors was associated with lethal progression of the disease if the tumors expressed low vitamin D receptor (VDR) levels, but not if the tumors had high VDR levels." (PMID 27803671, 2016). "The link tumour/calcium receptors/manganese could provide functional information related to the high potential metastatic risk of breast or prostate tumours CaSR expressing." (PMID 32931488, 2020). "Moreover, the molecular mechanisms underlying the enhanced expression of CaSR in breast and prostate tumors that implicates an oncogenic role for CaSR in these tissues have yet to be deciphered." (PMID 27679579, 2016). "The immunohistochemistry analysis of prostate tumours demonstrated a very low expression level of CaSR and TRPV6 with a score between 0 and 1 (2E 2I and 2L)." (PMID 32931488, 2020). "By using quantitative MEMRI, this work has demonstrated the potential of manganese for different types of breast or prostate tumour animal models in presence of different CaSR or TRPV6 level expression." (PMID 32931488, 2020). "CaSR exhibits high expression levels within prostate tumors." (PMID 38920679, 2024).
uremia (4 papers, 2012 to 2025). A clinical syndrome associated with the retention of renal waste products or uremic toxins in the blood. "At time of investigation after 7 weeks of uremia, CASR immunostaining was significantly decreased in both untreated CKD groups compared to both control groups." (PMID 39761264, 2025). "In the setting of uremia, decreased expression of CaSR was not only observed in parathyroid gland cells, but also in blood cells." (PMID 34828498, 2021). "Interestingly, parathyroid hormone secretion decreased significantly after reversal of uremia by homogeneic renal transplantation, while the expression of CaSR and VDR genes in parathyroid glands remained decreased." (PMID 36267284, 2022).
ankylosing spondylitis (3 papers, 2020 to 2025). An autoimmune chronic inflammatory disorder characterized by inflammation in the vertebral joints of the spine and sacroiliac joints. "This study identifies a critical role of inflammation‐induced aberrant upregulation of CaSR in the process of pathological new bone formation in ankylosing spondylitis (AS)." (PMID 33259138, 2020). "Interestingly, when CaSR expression was aberrantly upregulated in entheseal cells, pathological new bone formation was stimulated and resulted in ankylosing spondylitis." (PMID 33396907, 2020).
astrocytoma (3 papers, 2014 to 2018). "Also in astrocytoma cells and ovarian cells, CaSR activation induced proliferation and functioned as an oncogene." (PMID 24576174, 2014).
autoimmune disease (3 papers, 2010 to 2023). A disorder resulting from loss of function or tissue destruction of an organ or multiple organs, arising from humoral or cellular immune responses of the individual to their own tissue constituents. "An autoimmune HP is very likely if associated with the presence of antibodies against parathyroid autoantigens (calcium-sensing receptor, CaSR; NACHT leucine-rich-repeat protein 5, NALP5), other autoimmune disorders, or organ-specific antibodies." (PMID 36980146, 2023).
autosomal dominant polycystic kidney disease (3 papers, 2018 to 2025). Autosomal dominant form of polycystic kidney disease. "CaSR activation has also been proven to play a positive role in correcting some alterations found in cell models of Autosomal Dominant Polycystic Kidney Disease (ADPKD)." (PMID 31717830, 2019).
bone metastasis (3 papers, 2018 to 2020). Transfer of a neoplasm from its primary site to bones. "The calcium-sensing receptor (CaSR) has been associated with bone metastasis in several different malignancies." (PMID 29644008, 2018). "Although there is a need for confirming an unequivocal role of the CaSR in bone metastasis, we can still speculate the mechanisms by which the bone microenvironment might act through the CaSR in promoting osteolysis or bone metastases." (PMID 32117726, 2020).
cholera (3 papers, 2018 to 2024). "The novel pathway for modulating intestinal Cl− secretion through the colonic CaSR may lead to new pharmaco-nutritional therapies for prevention or treatment of certain clinical diarrheal diseases (i.e., cholera and other cyclic nucleotide-associated diarrheal diseases)." (PMID 29777154, 2018). "Although CaSR activation is a promising treatment strategy for secretory diarrheas, and short-term cinacalcet use for cholera might provide marked clinical benefits, long-term cinacalcet use for chronic diarrheas can cause systemic side effects due to CaSR activation in other organs." (PMID 37962961, 2024). "Here, we provide evidence that activation of CaSR by cinacalcet in a human colonic cell line and in mouse intestine inhibits intestinal fluid secretion and enhances fluid absorption, offering a simple, novel, and rapidly translatable therapeutic strategy for secretory diarrheas, including cholera." (PMID 33400691, 2021). "Nonetheless, the ability of CaSR agonists to reduce cholera toxin-induced fluid secretion demonstrated in this and other studies highly suggests that this class of nutrients and drugs may provide a unique therapy for cholera and other secretory diarrheal diseases." (PMID 29777154, 2018). "Here we showed that CaSR regulates CFTR-mediated Cl– secretion in human T84 cells, and the FDA-approved CaSR activator cinacalcet prevents intestinal fluid accumulation in mouse models of cholera and traveler’s diarrhea." (PMID 33400691, 2021).